LDHA (lactate dehydrogenase A)
Diseases named in the same sentence as LDHA in open-access papers (continued):
Sharing a sentence is not in itself a finding about the gene and the disease.
breast cancer (continued). "Furthermore, quercetin suppresses glycolysis by downregulating PKM2, glucose transporter 1 (GLUT1), and lactate dehydrogenase A (LDHA) in MCF-7 and MDA-MB-231 human breast cancer cell lines." (PMID 34445360, 2021). "Additionally, ENO1 and LDHA were reported to promote the EMT and stemness in lung and breast cancer cells, suggesting that upregulation of glycolytic genes by YBX1 plays a crucial role in promoting tumor aggressiveness." (PMID 34440660, 2021). "ETV4 knockdown also downregulated HK2, LDHA and PDK1 protein levels in breast cancer cells." (PMID 34052833, 2021). "However, the activity of LDH and expression of lactate dehydrogenase A (LDHA) were comparable between OC-treated breast cancer and control cells." (PMID 32934344, 2020). "Also, high glucose consistently triggered HK2 and LDHA expression and stimulated the USP28/MYC axis in breast cancer cells." (PMID 30688660, 2019). "In addition, P4HA1 expression significantly correlated with mRNA levels of LDHA and PDK1 in human breast cancer tissue." (PMID 30367042, 2018). "Similar results were observed in a study of LDHA silencing in breast cancer cell line, where stable LDHA knock down did not affect cell viability, lactic acid production, glucose consumption, or ATP." (PMID 29326883, 2017). "qRT-PCR analysis was used to detect the expression of LDHA in 9 different mammary cell lines, including the human mammary epithelial (HME) cell line (MCF-10A) and human breast cancer cell lines (SKBR3, BT-474, BT-483, T47D, MCF-7, MDA-MB-468, MDA-MB-231, MDA-MB-435)." (PMID 26902416, 2016). "Our data suggest that the overexpression of Twist in breast cancer cells may result in EMR through up-regulating of PKM2, LDHA, and G6PD." (PMID 26342198, 2015). "In metastatic 66cl-4 breast cancer cells, LDHA levels were highest in CN (100%) and CH (75%) cells, but expression of LDHA in control cells was not hypoxia-dependent." (PMID 26536104, 2015). "As CCL2, HGF and CCL2/HGF treatment of breast cancer cells led to differences in glucose metabolism, we examined for expression of glycolytic proteins over time, including glucose transporter 1 (GLUT1) and rate limiting enzymes HK2, lactate dehydrogenase (LDHA) and pyruvate kinase M (PKM)." (PMID 40736024, 2025). "The activation of lactate dehydrogenase A (LDHA) promotes the production of lactate and reduces the pH value, guiding the ubiquitination and stabilization of MYC mediated by the ubiquitinase to activate the SLUG promoter, which strengthens the characteristics of CSCs in breast cancer." (PMID 38561775, 2024). "After a treatment with 0.1 and 0.2 mM diclofenac LDH activity and LDHA/B protein levels were significantly reduced in LS174T and LoVo colorectal cancer cells, but remained unaltered in A549 lung cancer, MDA-MB-231 breast cancer and COLO357 pancreatic cancer cells." (PMID 38229111, 2024). "Papaverine, an isoquinoline-type alkaloid reported to inhibit LDHA, is currently undergoing clinical trials as a radiosensitizer aimed at reducing tumor hypoxia and enhancing the radiotherapy response in A549 non-small cell lung cancer cell (NSCLC) and EO771 breast cancer xenografts." (PMID 37915411, 2023). "In addition, AMPK protein levels have been positively correlated with the overexpression of lactate dehydrogenase A (LDHA) in triple-negative breast cancer (TNBC) cells and breast cancer tissues, and this has been attributed to increased glucose intake and efficient glycolysis." (PMID 36677797, 2023). "As the expression of DIO3OS increases in breast cancer cells undergoing AI resistance, the aberrant activation of DIO3OS/PTBP1/LDHA glycolysis cascade may endow tumor cells with metabolic adaptation that allows them to survive from AI-caused estrogen deficiency." (PMID 36418319, 2022).
breast cancer (continued). "BA could inhibit c-myc-induced glycolytic activation and inhibited protein expression of c-Myc, LDHA, and p-PDK1/PDK1 in MCF-7 and MDA-MB-231 cells in vitro and mice breast cancer model suggested that BA is a good candidate for the glycolysis inhibitor in vivo." (PMID 36339566, 2022). "Since LDHA is a critical enzyme for the conversion of pyruvate to lactate at the final step of aerobic glycolysis, we set out to determine whether LDH activity was modulated by SIPA1 in breast cancer cells." (PMID 35096814, 2021). "However, there has been study showing that silencing LDHA failed to alter lactic acid production in breast cancer cell line." (PMID 34178639, 2021). "Transcript levels of five of the seven metabolic genes (TALDO1, GPI, SHMT2, LDHA, and ADK: 5-gene metabolic signature) and six oncogenes: TAGLN2, NOLC1, HSP90AB1, HDGF, MCM5, and NCL, were elevated in TNBC patients when compared to patients with ER+ breast cancer." (PMID 34711841, 2021). "By contrast, incubation with OC did not influence the level of LDHA in breast cancer cells." (PMID 32934344, 2020). "Similarly, primary marrow fat cells and adipocyte cell lines trigger metabolic reprogramming of bone metastatic prostate cancer cells by enhancing the expression of PDK1, enolase 2 (ENO2), LDHA as well as HK2 and GLUT1, already mentioned as Notch downstream effectors in breast cancer cells." (PMID 30873026, 2019). "Phosphorylation in Y10 increases LDHA activity by enhancing the active tetrameric LDHA conformation, which induces the binding of NADH and promotes Warburg effect in human head and neck squamous cell carcinoma (HNSCC), lung cancer, breast cancer and prostate cancer cells." (PMID 31737570, 2019). "KD of LDHA was reported to contribute to the increase of mitochondrial ROS, because of the redirection of metabolism away from lactate as the end product, favouring rather the conversion of pyruvate to acetyl-coA and entering the TCA cycle in mitochondria for breast cancer." (PMID 27708237, 2016). "Moreover, we analyzed the correlation between the levels of LDHA and miR-34a in 22 breast cancer tissues and detected a negative correlation between them." (PMID 26902416, 2016). "The gene expression analyzed are: 1) LDHA is relatively highly expressed in luminal, HER2+, and triple-negative breast cancers in the different subclasses of breast cancers." (PMID 36072431, 2022). "Unlike LDHA, LDHB is negligibly expressed in luminal breast cancer cells like MCF-7 and its knockdown had no major effect on cell proliferation." (PMID 34158867, 2021). "Overall, sensitivity of cells to LDH inhibition as measured by lactate flux varied greatly between cell lines and did not correlate with levels of either LDHA or LDHB expression, except in breast cancer." (PMID 24280423, 2013). "Furthermore, when we examined LDHA levels in 14-3-3ζ overexpressing established breast cancer cell lines such as, HCC1954 HER2+ and MDA-MB-231 TNBC, we did not detect a significant up-regulation of LDHA or increase of glycolysis (data not shown)." (PMID 27150057, 2016). "Similarly, in MCF7 breast cancer cells SLC2A1, HK2, and PFKFB3 but not ENO1 or LDHA were strongly induced by hypoxia." (PMID 23866118, 2013). "Using transcriptome sequencing data of the CSC subpopulation in SUM149 human breast cancer cell line from GSE132083, we compared the glycolytic gene expression profiles between the CSC group and non-CSC group, and found that SLC2A1, HK2, ALDOA, ENO1, LDHA and PDK1 were upregulated in the CSC group." (PMID 34052833, 2021).
pancreatic cancer (149 papers, 2012 to 2026). "Our present findings showed a mechanism underlying the regulation of LDHA expression, which involved the post-transcriptional regulation by miR-4259 in pancreatic cancer cells." (PMID 39930542, 2025). "Substituting endogenous LDHA with a palmitoylation-deficient mutant suppresses pancreatic cancer proliferation, increases tumor-infiltrating T cells, limits tumor growth, and alters chemotherapy response." (PMID 40977744, 2025). "Apart from citric acid metabolism, LDHA expression has also been associated with gemcitabine resistance in pancreatic cancer." (PMID 38425123, 2024). "The overexpression of LDHA in pancreatic cancer is also associated with poor prognosis and resistance to standard chemotherapeutic regimes." (PMID 38425123, 2024). "According to our research, individuals with pancreatic cancer who were in the low-expression group had a much greater chance of surviving than those in the high-expression group, with the most significant LDHA being linked to glycolytic metabolism." (PMID 36814901, 2023). "For instance, KRAS mutations which are widely detected in pancreatic cancers and colon cancers mediate multiple key glycolysis enzymes (such as HK-I/II, LDHA and GLUT1) thus leading glucose metabolism reprogramming." (PMID 37187730, 2023). "Abnormal expression and upregulation of LDHA are closely associated with a variety of cancers and can be used as a sensitive prognostic factor for lung, liver and pancreatic cancers." (PMID 36447119, 2023). "Patients with pancreatic cancer in the low-expression group had a much higher survival rate than those in the high-expression group, with the LDHA associated with glycolysis being the most significant (p < 0.001)." (PMID 36814901, 2023). "In that sense, it is interesting to note that nuclear LDHA is more prevalent in human pancreatic cancer tissue than in normal tissue and that higher LDHA levels are associated with poorer survival prognosis of pancreatic cancer patients." (PMID 37779146, 2023). "FOXM1 belongs to the Forkhead transcriptional superfamily, found positively associated with LDHA in pancreatic cancer." (PMID 36407005, 2022). "LDHA was also associated with a poor prognosis in pancreatic cancer by regulating the expression of L-2 hydroxyglutarate, an epigenetic modifier, which can inhibit T cell proliferation and migration and thereby contribute to immune escape." (PMID 34393804, 2021). "Apparently, the overexpression of LDHA or PKM2 restored the inhibition of pancreatic cancer cell growth and glycolysis caused by overexpression of miR-489-3p." (PMID 34868902, 2021). "Together, these results suggest that LDHA overexpression is associated with clinical disease progressions and malignant behaviors of pancreatic cancer." (PMID 34185423, 2021). "High LDHA expression has been reported in a number of malignancies, including pancreatic cancer, and has been associated with tumor development, invasion, and metastasis." (PMID 31527446, 2019). "In addition, lactic acidosis caused by the SIX1/LDHA axis contributes to NK cell dysfunction in pancreatic cancer." (PMID 40165895, 2025). "Furthermore, experiments demonstrated that LDHA deficiency in pancreatic cancer elevated the CD8+ T cell antitumor immunity and improved macrophage antitumoral polarization, which in turn enhanced the efficacy of immunotherapy." (PMID 38664705, 2024). "Furthermore, we also found that the expression of TES and LDHA was significantly associated with survival of pancreatic cancer patients." (PMID 35789607, 2022). "To further investigate the association of LDHA expression with L‐lactate production in pancreatic cancer, we measured the intracellular and extracellular L‐lactate concentration by lactate assays and performed in vitro LDH release assay to assess the LDH enzymatic activity in PAAD cells." (PMID 34185423, 2021).
pancreatic cancer (continued). "Although additional studies are needed for pancreatic cancer, our study showed that there is a progressive increase in lactate accumulation inside the cells during tumor progression that is linked to an increase in LDHA expression in pancreatic cancer." (PMID 31861288, 2019). "Indeed, we have shown that increased expression of both PKM2 and LDHA can contribute to the initiation and progression of pancreatic cancer and is associated with poor prognosis." (PMID 31527446, 2019). "Furthermore, a recently published study confirmed that PKM2 and LDHA also play a key role in pancreatic cancer-associated fibroblasts (CAFs) metabolism." (PMID 31527446, 2019). "Cui et al25 found FOXM1 level was positively associated with LDHA in pancreatic cancer." (PMID 30403008, 2018). "As our clinical analysis showed a positive correlation between serum LDH‐5 level and a larger tumor size, the presence of liver metastasis, and a more advanced disease stage in pancreatic cancer patients, we hypothesized that its encoding gene, LDHA, may regulate pancreatic cancer progression." (PMID 34185423, 2021). "Since alteration of glucose metabolism is one of the hallmarks of cancer cells, we proposed that pyruvate kinase type M2 (M2PK) and lactate dehydrogenase A (LDHA) enzymes could represent novel diagnostic markers and potential therapeutic targets in pancreatic cancer." (PMID 26989901, 2016). "The results demonstrated that treatment inhibited organoid growth and reduced the organoid area in a dose-dependent manner, indicating that LDHA inhibition effectively targeted the clonogenic capacity of pancreatic cancer cells." (PMID 41554705, 2026). "In this study, we uncovered that the repression of LDHA by FOXO3a-mediated miR-4259 expression suppresses the gemcitabine resistance and cancer stemness of pancreatic cancer." (PMID 39930542, 2025). "We also found the transcriptional regulation of miR-4259 by FOXO3a and the clinically relevant relationship among LDHA, miR-4259 and FOXO3a in pancreatic cancer that was related to the response to gemcitabine treatment." (PMID 39930542, 2025). "For example, lysine acetylation of LDHA was found to stabilize the LDHA protein level and is also involved in the progression of pancreatic cancer." (PMID 39930542, 2025). "FOXQ1 promotes pancreatic cancer cell proliferation, tumor stemness, invasion, and metastasis through regulation of LDHA-mediated aerobic glycolysis." (PMID 40141294, 2025). "By examining the Oncomine database, we observed that LDHA was significantly increased in human pancreatic cancer compared with normal pancreatic tissue, and positively correlated with high grade, advanced stage and metastatic pancreatic cancer." (PMID 39930542, 2025). "Several inhibitors have been identified, including oxamate, which competitively binds to the active site of LDHA, displacing pyruvate and significantly reducing lactate production in pancreatic cancer cells." (PMID 41007358, 2025). "This suggests that the regulation of LDHA by microRNAs impacts the chemosensitivity and cancer stemness of pancreatic cancer." (PMID 39930542, 2025). "In a pancreatic cancer study, Liang found that the Kla modification of nucleolar and spindle-associated protein 1 (NUSAP1) regulates LDHA expression, establishing a positive feedback loop involving NUSAP1 Kla, LDHA, glycolysis, and lactate." (PMID 40755753, 2025). "Recent studies also find that FOXM1 upregulates LDHA transcription to enhance lactate production and promote cancer growth and metastasis, whereas KLF4 negatively regulates LDHA gene expression and is involved in the progression of pancreatic cancer." (PMID 39930542, 2025). "Klf4 binds to the promoter region of LDHA, thus regulating LDHA expression in pancreatic cancer cells." (PMID 40593465, 2025). "Taken together, these results indicated that miR-4259 is transcriptionally regulated by FOXO3a to further suppress the LDHA expression in pancreatic cancer cells." (PMID 39930542, 2025).
pancreatic cancer (continued). "have uncovered that ZDHHC9-mediated palmitoylation of LDHA enhances lactic acid production, thereby promoting the proliferation and growth of pancreatic tumor cells." (PMID 40165895, 2025). "We further observed that LDHA expression inversely correlated with the levels of miR-4259 and FOXO3a in recurrent pancreatic cancer following gemcitabine treatment." (PMID 39930542, 2025). "GEM resistance commonly occurs in pancreatic cancer, potentially due to the upregulation of LDHA mediated by the family with sequence similarity 83 (Fam83)." (PMID 40264038, 2025). "In-vitro studies have demonstrated that targeting LDHA can reduce the proliferation, migration, and invasion of pancreatic cancer, and in-vivo studies have shown that tumor growth is decreased." (PMID 40091035, 2025). "Our findings provide evidence of a novel function and regulatory mechanism of LDHA that is involved in the cancer stemness and gemcitabine resistance of pancreatic cancer." (PMID 39930542, 2025). "FOXQ1 via promotes the transcription of Lactate dehydrogenase A (LDHA) and increases its expression in pancreatic cancer (PC)." (PMID 41347087, 2025). "We observed that elevated LDHA expression significantly correlates with recurrent pancreatic cancer patients following gemcitabine treatment and with CSC properties." (PMID 39930542, 2025). "The IHC in Human Protein Atlas (HPA) datasets also revealed the elevated protein expression level of LDHA in cervical cancer, kidney cancer, lung cancer and pancreatic cancer." (PMID 38664705, 2024). "Synergetic interactions have been described between LDHA inhibitors and gemcitabine treatment in hypoxic pancreatic cancer." (PMID 38425123, 2024). "FOXM1 upregulation raised LDHA levels, glucose utilization, and lactate production and facilitated pancreatic cancer cell growth." (PMID 39060874, 2024). "Higher LDHA expression has been found to be positively connected with malignant progression in many cancers such as gastric, gallbladder, pancreatic cancer, nasopharyngeal cancer and HCC." (PMID 38229475, 2024). "Subsequent investigation into LM.SIG identified the LDHA as the most potential therapeutic target in pancreatic cancer." (PMID 38664705, 2024). "Extensive literature data have confirmed that aberrant expression and activation of LDHA is closely related to liver cancer, pancreatic cancer, nasopharyngeal cancer and other cancers." (PMID 38163874, 2024). "In pancreatic cancer, 13C3‐lactate carbon is used for acetylation of histone H4, a process that is dependent on nucleologically localized LDHA." (PMID 39184862, 2024). "In pancreatic cancer, hyperglycemia induces the accumulation of hypoxia-inducible factor 1α, leading to increased lactate dehydrogenase A (LDHA) activity and expression." (PMID 39290325, 2024). "Highly expressed UCHL3 is critical for aerobic glycolysis in pancreatic cancer because it stabilizes tumor promoter LDHA (lactate dehydrogenase A) expression." (PMID 37740194, 2023). "In our study, we found that LDHA can be used as a telomere-related gene to accurately predict the prognosis of pancreatic cancer patients." (PMID 37391503, 2023). "K5 acetylation of LDHA is known to decrease LDHA level by inducing lysosomal degradation of LDHA in human pancreatic cancer." (PMID 35278714, 2023). "Higher nuclear LDHA localization is observed in pancreatic cancer than in normal tissues, showing disease relevance." (PMID 37779146, 2023). "Normal pancreatic tissues minimally expressed LDHA, whereas most of the pancreatic cancer tissues exhibited high expression with more nuclear localization of LDHA." (PMID 37779146, 2023). "Acetylation at K5 of LDHA in human pancreatic cancer increases the lysosomal degradation of LDHA, and LDH activity was inhibited." (PMID 35278714, 2023). "Researchers analyzed The Cancer Genome Atlas (TCGA) database and identified the remarkably higher LDHA methylation in pancreatic cancer tissues." (PMID 36518315, 2022).